NTRK1 (neurotrophic receptor tyrosine kinase 1)
Diseases named in the same sentence as NTRK1 in open-access papers (continued):
Sharing a sentence is not in itself a finding about the gene and the disease.
sarcoma (36 papers, 2012 to 2026). A usually aggressive malignant neoplasm of the soft tissue or bone. "Our cohort also included five sarcoma samples harboring an NTRK1 or NTRK3 fusion, which is predictive of response to the FDA-approved drugs entrectinib, larotrectinib, and repotrectinib." (PMID 40711866, 2025). "A comprehensive literature search was conducted in PubMed, Embase, and Web of Science databases using the terms (“LMNA::NTRK1” OR “LMNA-NTRK1 fusion”) AND (“spindle cell neoplasm” OR “soft tissue tumor” OR “sarcoma”) from January 2016 to March 2025." (PMID 41409361, 2025). "NTRK1/2/3 gene fusions encode TRK fusion proteins, serving as oncogenic drivers in multiple solid tumors, including lung, thyroid, salivary gland, and sarcoma." (PMID 39055566, 2024). "NTRK1–3 gene fusions are relatively frequent in some pediatric tumors and sarcomas, although they are exceptionally rare in common cancer types." (PMID 37686416, 2023). "NTRK1–3 fusions have now been identified in a number of different tumor types, including sarcomas, carcinomas, and hematologic malignancies in adults and children." (PMID 34531526, 2022). "While morphologically high-grade NTRK1-fused tumors display an aggressive course in the majority of the cases, morphologically low-grade NTRK1-fused sarcomas can have a favorable clinical course." (PMID 35645621, 2022). "Fusions of the NTRK1 gene also occur in low-grade sarcomas with a distinctive myopericytoma- or hemangiopericytoma-like morphology." (PMID 33803146, 2021). "The most logical approach would be to lump all of these lesions under the rubric of “TRK-fusion associated tumor of intermediate malignant potential” to include both LPF-like neural tumors and IFs as well as NTRK1 fusion sarcomas." (PMID 30613391, 2018). "Rare NTRK1/2/3 fusions were identified in two sarcoma subtypes, suggesting NTRK-directed therapies might be of benefit in these cases." (PMID 40711866, 2025). "By RNA sequencing, the expression of LMNA::NTRK1 in the hES-MP background resulted in a transcriptional signature with enrichment of genes involved in neuronal and neural crest function, as well as other upregulated in sarcoma datasets, such as Ewing sarcoma." (PMID 36801905, 2023). "In a recent large study of sarcoma, CGP identified potentially actionable kinase fusions (including NTRK1‐3, ALK, BRAF, FGFR1‐4, RET, and ROS1) in 2.6% of patients." (PMID 38925616, 2024). "These included ALK, BRAF, FGFR1–4, NTRK1–3, RET, and ROS1 kinase fusions in a wide range of sarcoma histologies, including IMT (62.1%), MPNST (4.9%), UPS of bone (4.3%), extraskeletal osteosarcomas (4%), UPS (3.6%), sarcoma NOS (3.8%), and LMS (1.9%)." (PMID 35705558, 2022). "The prognosis of NTRK1- and NTRK3- fused sarcomas in correlation with histomorphology, has also been a subject of investigation." (PMID 35645621, 2022). "The investigators stress the fact that, in contrast to the low cellular NTRK1 fused sarcomas, the low-intermediate grade NTRK3 fused sarcomas can be aggressive neoplasms giving rise to metastatic disease." (PMID 33803146, 2021). "The second category of NTRK1 fused tumors was further subdivided into low-grade CD34 and S100 protein positive tumors and into high-grade unclassified sarcomas." (PMID 33803146, 2021). "On the other hand, molecular profiling NTRK1/3 fusions in other pediatric tumors such as those of mesenchymal origin such as sarcomas is not well studied." (PMID 35860155, 2022). "Actionable kinase fusions in sarcoma have not been comprehensively described with the exception of ALK fusions in inflammatory myofibroblastic tumors (IMT) and NTRK1–3 fusions in infantile fibrosarcoma." (PMID 35705558, 2022). "In conclusion, we report two cases of NTRK1 fusion-positive and seven cases of NTRK3 fusion-positive pediatric sarcomas and IMT that were diagnostically challenging without molecular features." (PMID 32957984, 2020).
papillary thyroid carcinoma (34 papers, 2000 to 2026). "Other potential targetable genetic alterations were found in less than 10% cases: the RET gene fusion was found in 8%, NTRK1 and 3 gene fusion in 3%, and other mutations in less than 2% of classic papillary thyroid cancers." (PMID 34630336, 2021). "TFG is at 3q12, also known as the tropomyosin-receptor kinase fused gene or TRK fusion gene, and it was first discovered as a fusion partner of NTRK1 in human papillary thyroid carcinoma." (PMID 36408177, 2022). "Subsequently, NTRK1 fusions have been detected at a frequency of 12% in papillary thyroid cancer with TPM3-NTRK1 being the most common gene rearrangement." (PMID 26472021, 2015). "In up to 12% of papillary thyroid cancer patients, the 3′ exons of NTRK1 with the kinase domain had been found to fuse with the 5′ exons of various thyroid-expressed genes (TPM3, TPR, TFG) in frame." (PMID 24647444, 2014). "Rearrangements of the NTRK1 gene are consistently observed in a small fraction of papillary thyroid carcinomas." (PMID 24261984, 2013). "The incidence of NTRK1 translocations is exclusive to papillary thyroid cancer, but with a much lower frequency (5–15%) than RET translocations or BRAF point mutations." (PMID 24281099, 2010). "Papillary thyroid carcinomas (PTC) frequently harbor activating rearrangements of RET (8–33%) or NTRK1 (5–15%) genes, both coding for receptor tyrosine kinases that exert control over a wide range of transcription factors." (PMID 19087340, 2008). "Rearrangements of NTRK1 proto-oncogene were detected in ‘spontaneous’ papillary thyroid carcinomas with a frequency varying from 5 to 25% in different studies." (PMID 10646882, 2000). "In the ‘spontaneous’ tumours, only one of the 14 papillary carcinomas and one of the four in vitro culture cell lines, derived from a papillary carcinoma, presented a NTRK1 rearrangement also with the TPM3 gene." (PMID 10646882, 2000). "Our results concerning the radiation-associated tumours showed that only rearrangements between NTRK1 and TPM3 genes (TRK oncogene) were detected in 2/14 papillary carcinomas and in one lymph-node metastasis of one of these papillary thyroid carcinomas." (PMID 10646882, 2000). "TPM3 also leaded to papillary thyroid carcinoma via rearrangement with NTRK1." (PMID 36639822, 2023). "Furthermore, expression of NTRK1 rearrangements in papillary thyroid cancer also confers a worse prognosis when compared to patients without this fusion gene." (PMID 29617282, 2018). "It will be interesting to understand if this fusion is specific to CRC or it is also present in other tumor types, such as non small cell lung cancer, papillary thyroid carcinoma and glioblastomas, where multiple NTRK1 rearrangements have already been identified." (PMID 28903424, 2017). "A number of gene alterations, such as point mutations in RAS and BRAF genes, point mutations or amplification of PIK3CA, and fusion genes involving RET, NTRK1 and PPARγ are known to frequently occur in differentiated thyroid carcinoma, and are correlated to different morphological subtypes." (PMID 22087789, 2011). "Common in papillary carcinoma of children and young adults (NTRK3 fusion, ~ 15%; NTRK1 fusion, ~ 5%)." (PMID 38108848, 2024). "Among pediatrics there was one case each of fibrosarcoma (TPM3::NTRK1), Ewing’s sarcoma (LPPR1::NTRK2), primitive neuroectodermal tumor (DAB2IP::NTRK2), and papillary thyroid carcinoma (RAD51B::NTRK3)." (PMID 38967220, 2024). "The other molecular alterations that are less frequent in papillary thyroid carcinomas are E1F1AX, ALK fusion, NTRK1, or NTRK3 fusion." (PMID 36980552, 2023). "TFG was first identified to fused to the 3’ end of NTRK1 and generate the TRK-T3 fusion transcript in papillary thyroid carcinoma." (PMID 35091545, 2022).
papillary thyroid carcinoma (continued). "Since this observation, gene fusions involving NTRK1, 2, and 3 genes have been documented in 11 specific tumor types, most notably NSCLC, papillary thyroid carcinoma, secretory breast cancer, and glioblastoma." (PMID 29617282, 2018).
pancreatic cancer (33 papers, 2008 to 2026). "More research is needed to see the efficacy of NTRK1 inhibitors in pancreatic cancer, especially acinar cell carcinoma." (PMID 39410042, 2024). "A cell viability assay showed that the ectopic expression of BRAFV600E in an NTRK1 fusion-positive pancreatic cancer cell line maintained a strong proliferation trend under LOXO-195 treatment conditions." (PMID 38318928, 2024). "The transcripts per million reads (TPM) level of NTRK1 was found to be lower in the lung, breast, prostate and pancreas cancers when compared to their normal state." (PMID 38635549, 2024). "Additionally, using data from the Cancer Genome Atlas, it was found that 48% of pancreatic cancer patients had alterations in genes related to neuroactive molecules or their receptors, with the most notable change being in the neurotrophic receptor tyrosine kinase 1 (NTRK1) gene, which encodes TrkA." (PMID 40940782, 2025). "The discovery of recurrent fusions involving NRG1 in KRAS wild-type pancreatic tumors, as well as case reports of fusions involving BRAF, PRKACA, NTRK1/3, and RET, prompted us to systematically screen for fusion genes in this cancer entity." (PMID 33441414, 2021). "When applied to a large collection of published pancreatic cancer samples (n = 803), Arriba identified a variety of driver fusions, many of which affected druggable proteins, including ALK, BRAF, FGFR2, NRG1, NTRK1, NTRK3, RET, and ROS1." (PMID 33441414, 2021).
Alzheimer disease (32 papers, 2011 to 2026). A progressive, neurodegenerative disease characterized by loss of function and death of nerve cells in several areas of the brain leading to loss of cognitive function such as memory and language. "However, this latent form can be reactivated by NGF deprivation, and NGF promotes viral latency via the TrkA receptor NTRK1, the expression of which is reduced in the Alzheimer's disease brain." (PMID 22254144, 2011). "Very interestingly, NTRK1/NTRKA protein levels are reduced in the cortex of Alzheimer’s disease patients, while many studies report no change in p75/NGFR levels." (PMID 32575701, 2020).
prostate carcinoma (31 papers, 2007 to 2025). A carcinoma that arises from epithelial cells of the prostate gland. "This and two other studies of the NTRK1 sequence: in prostate cancer and medullary thyroid carcinoma, utilised SSCP as the sole screening method." (PMID 20003389, 2009). "Since gene fusions—including ETS transcription factors and NTRK1—are common in human prostate cancer, we investigated whether TRAMP tumors would harbor fusion genes, again using RNA sequencing." (PMID 35159020, 2022). "In prostate cancer, the NGF stimulates NTRK1 downstream of p38-MAPK activation to promote cell migration, invasion, and metastasis." (PMID 33398073, 2021). "In prostate cancer, the development of NGF/NTRK1 or BDNF/NTRK2 autocrine signaling pathways is an escape mechanism, from both the androgen control and the paracrine dependence of stromal cells produced neurotrophins." (PMID 29904026, 2018). "Similar to previous findings in prostate cancer, cancer cell nests containing both NGF and NTRK1 suggested an important autocrine tumor maintenance function of this system in HNSCC." (PMID 29904026, 2018). "In addition to NTRK1 and the NGFR, we identified a mechanism which is involved in ADT-mediated neuroendocrine differentiation in prostate cancer via CHRM4 upregulation." (PMID 33398073, 2021). "This suggests that NTRK1 and the NGFR might not respond to AR signaling, and the roles of NGF–NGFR or NGF–NTRK1 signaling pathways might differ from that of NGF–CHRM4 signaling in prostate cancer." (PMID 33398073, 2021).
glioblastoma (30 papers, 2011 to 2026). The most malignant astrocytic tumor (WHO grade IV). "We demonstrate a unidirectional regulatory hierarchy wherein NTRK1 transcriptionally governs IGF2 to amplify proteotoxic stress, a mechanism previously documented in glioblastoma but newly implicated in pain neuroscience." (PMID 40722704, 2025). "TRK proteins (including TRKA, TRKB, and TRKC) are encoded by the NTRK gene family (NTRK1-3), which are frequently fusion-positive in a broad range of solid tumors, including glioblastoma, NSCLC, and STSs." (PMID 36209184, 2022). "Here the authors describe an approach to generate engineered mouse models carrying specific gene fusions and, as a proof of principle, show that Bcan-Ntrk1 fusion leads to glioblastomas." (PMID 28695888, 2017). "NTRK1 fusions are now known to occur in many other solid tumor types, including lung adenocarcinoma, papillary thyroid carcinoma, secretory breast carcinoma, and glioblastoma (GBM)." (PMID 32906676, 2020). "This paradigm, observed in glioblastoma but previously unreported in pain neuroscience, manifests maladaptively in CPSP as NTRK1-induced IGF2 overexpression exacerbates ER stress, creating a pathogenic feedforward loop." (PMID 40722704, 2025). "Similarly, the LMNA–NTRK1 fusion showed an over 70-fold overexpression of NTRK1, comparable to the high LMNA expression from glioblastoma." (PMID 38254850, 2024).
lung adenocarcinoma (24 papers, 2014 to 2025). A carcinoma that arises from the lung and is characterized by the presence of malignant glandular epithelial cells. "We present a case of a lung adenocarcinoma patient harboring a novel kinesin family member 5B (KIF5B)-NTRK1 gene fusion that responds well to entrectinib." (PMID 39590120, 2024). "Currently, approximately 60% of lung adenocarcinomas have now been shown to have mutations (KIF5B-Ret, ROS1, NTRK1, HER2-Neu, to name a few) that may induce and drive these malignancies and the association of TTF-1 status and presence of these driver mutations remains to be elucidated." (PMID 25594059, 2014). "Other therapeutic targets included NTRK1 and NKX2-1, both of which were discovered as targetable oncogenes and promising results in lung adenocarcinoma have been reported." (PMID 30018380, 2018). "In lung adenocarcinoma, rearranged genes, including ALK, ROS1, RET, NTRK1, and NRG1, have been reported." (PMID 28894699, 2017). "As for the other reference genes such as ROS1, HER2, RET, MET, NTRK1, NTRK2, and NTRK3, our study did not identify mutations in these genes in patients with lung adenocarcinoma." (PMID 38828424, 2024). "Furthermore, 23 newly NTRK1, NTRK2, and NTRK3 gene fusions were identified across different tumor types, including lung adenocarcinomas." (PMID 36289793, 2022). "As for other well-established driver alterations, HER2 mutation and amplification are less common in SCC compared to lung adenocarcinoma, while the prevalence of NTRK1/2/3 gene fusions do not vary across histologies." (PMID 35743191, 2022). "We observed no strong positive correlations for lung adenocarcinoma, providing evidence that the transcriptional effects of mutations in KRAS, EGFR, MET, NTRK1, and PIK3CA are distinct from each other." (PMID 29322935, 2017). "NTRK-1 fusions have been identified in 3 of 91 lung adenocarcinoma samples that were EGFR/KRAS/ALK-1/ROS-1 negative." (PMID 25505733, 2014).
non-small cell lung carcinoma (22 papers, 2015 to 2025). A group of at least three distinct histological types of lung cancer, including non-small cell squamous cell carcinoma, adenocarcinoma, and large cell carcinoma. "Beyond EGFR mutations, clinically relevant genetic alterations in non-small cell lung cancer (NSCLC) include fusions involving ALK, ROS1, RET, and NTRK1/2/3." (PMID 41301039, 2025).
acute myeloid leukemia (21 papers, 2007 to 2025). Acute myeloid leukemia (AML) is a group of neoplasms arising from precursor cells committed to the myeloid cell-line differentiation. "After evaluating gene expression in 59 patients with acute myeloid leukemia (AML), they observed upregulation of NTRK1 transcripts in 44% of the patients in the cohort." (PMID 31551508, 2019).
Cognitive impairment (21 papers, 2016 to 2026). Abnormal cognition is characterized by deficits in thinking, reasoning, or remembering. "In addition, we found neurotrophic tyrosine kinase receptor 1 (NTRK1), which is also implicated in neuronal damage, cognitive impairment and behavioral changes." (PMID 40619440, 2025). "Accordingly, NTRK1 could be a promising candidate therapeutic target in the treatment of cognitive impairment associated with hippocampal neuronal damage." (PMID 37907480, 2023). "Therefore, it was hypothesized that NTRK1 is involved in the regulation of hippocampal neuronal damage and the associated cognitive impairment." (PMID 37907480, 2023). "Resultantly, in vivo analysis revealed that NTRK1 knockdown induced mouse cognitive impairment and hippocampal tissue damage, in addition to inactivating the AMPK/ULK1/FUNDC1 pathway activity and mitophagy in the hippocampal tissues of mice." (PMID 37907480, 2023). "Mechanistically,NTRK1 knockdown might induce cognitive impairment and hippocampal neuron damage through the suppression of mitophagy via inactivating theAMPK/ULK1/FUNDC1 pathway." (PMID 37907480, 2023). "Abnormalities in NGF signaling caused by disruption of the structure of its receptors [TrkA (NTRK1 gene) and p75 (NGFR gene)] or the signaling pathways involved, may also impair brain morphogenesis and lay the groundwork for the onset of mental and cognitive disorders." (PMID 38646100, 2024). "A mouse NTRK1-knockdown model was established and subjected to pre-treatment with BAY-3827, followed by a behavioral test, Nissl staining, and NeuN immunofluorescence (IF) staining to evaluate the cognitive impairment and hippocampal neuronal damage." (PMID 37907480, 2023).
Arthritis (19 papers, 2008 to 2025). Inflammation of a joint. "NTRK1 has been shown to associate with other conditions related to aging and cognitive decline such as Parkinson’s disease, early AD subtype, arthritis, and hippocampal volume and cell survival, but literature support for the association between NTRK1 and AD directly remains limited." (PMID 40502754, 2025).